RNU6-122P (RNA, U6 small nuclear 122, pseudogene)
Gene: Small nuclear RNA gene on chromosome X (123,874,459 to 123,874,565, forward strand). Ensembl gene ENSG00000252627.
Homologues: Orthologues: chimpanzee U6 (100% identical), macaque U6 (73% identical), dog U6 (64% identical), rabbit U6 (64% identical), mouse Gm25792 (63% identical), guinea pig U6 (62% identical), rat LOC120103222 (53% identical). Paralogues in human: RNU6-20P (76% identical), RNU6-333P (76% identical), RNU6-830P (76% identical), RNU6-1091P (75% identical), RNU6-310P (75% identical), RNU6-35P (75% identical), RNU6-820P (75% identical), RNU6-851P (75% identical), RNU6-1152P (74% identical), RNU6-1244P (74% identical), RNU6-1249P (74% identical), RNU6-1310P (74% identical), and 1285 more.